KRAS (KRas proto-oncogene, GTPase)
Diseases named in the same sentence as KRAS in open-access papers (continued):
Sharing a sentence is not in itself a finding about the gene and the disease.
tumor (continued). "Although oncogenic mutations in KRAS and EGFR occur in a significant fraction of human LUAD, they are rarely—if ever—observed together in the same tumor." (PMID 26047463, 2015). "Surprisingly, our results show that STAT3 functions as tumour suppressor in KrasG12D/+ lung tumours as well as KRAS mutant human AC cell lines." (PMID 25734337, 2015). "Collectively, these results indicate that combination of let-7b repletion with paclitaxel or gemcitabine greatly compromises the migratory ability and invasiveness of KRAS mutant tumor cells and reverts the EMT phenotype." (PMID 25946136, 2015). "Inhibition of the MAPK/ERK pathway is a minimum requirement for suppression of mutant KRAS tumor cells." (PMID 25756961, 2015). "The same mutation was confirmed in 3 of these patients whilst the remaining 2 tumor samples tested WT for KRAS." (PMID 26498594, 2015). "Preclinical data suggest that combined MEK and PI3K inhibition will be required to enhance and prolong the anti-tumor activity of MEK inhibitors in KRAS-mutant colon cancers with alterations in the PI3K pathway." (PMID 26404261, 2015). "EGFR mutation, KRAS mutation and ALK-IHC were investigated in the 14 patients whose tumor specimens were available." (PMID 26682906, 2015). "We investigated 58 tumor samples from wild type KRAS CRC patients treated with cetuximab plus irinotecan (CI)." (PMID 26486455, 2015). "Genetic deletion of the autophagy protein ATG5 results in impaired progression of KRas(G12D)-driven lung cancer and promotes the survival of tumor bearing mice." (PMID 25617802, 2015). "We found that combination of let-7b repletion with paclitaxel or gemcitabine diminished both MEK/ERK and PI3K/AKT signaling in KRAS mutant tumor cells, leading to substantial increase in apoptosis." (PMID 25946136, 2015). "PEAK1 promotes tumor growth/metastasis and therapy resistance in human cancers via its regulation of the actin cytoskeleton and Src, KRas and ErbB2 signaling pathways." (PMID 26267863, 2015). "Further analysis revealed that more tumours with high granulocyte and low lymphocyte infiltration were found within KRAS mutant patient samples." (PMID 25734337, 2015). "Taken together, these results support the notion that let-7b synergizes with cytotoxins to arrest cell cycle and inhibit the proliferation of KRAS mutant tumor cells." (PMID 25946136, 2015). "Ixazomib concentrations in KRAS mutant tumors were either similar to or higher than those in KRAS WT tumors, and tumor proteasome β5-site activity was inhibited to a similar degree in both KRAS wild type and mutant tumors." (PMID 26709701, 2015). "Knockdown of TUBB3 using siRNA has been shown to significantly increase the cytotoxicity of paclitaxel and induce apoptosis in KRAS mutant tumor cells." (PMID 25946136, 2015). "One tumor sample (SRR396813) in the KRAS dataset was erroneously predicted to be normal by both DET- and DEE-based systems." (PMID 26356813, 2015). "In case P2, the BRAF p.V600E (c.1799 T > A) mutant allele frequency (29 %) was consistent with the estimated tumor cellularity (41–60 %), suggesting KRAS p.G15S (c.43G > A) was present in a subpopulation of tumor." (PMID 26498038, 2015). "While the molecular mechanism accounting for this selectivity remains to be fully elucidated, it is plausible that the downregulation of KRAS expression by let-7b is dependent on the stoichiometry between KRAS mRNA and let-7b in tumor cells." (PMID 25946136, 2015). "KRAS mutations and SEPT9 promoter methylation were present in 34% (29/85) and in 82% (70/85) of primary tumor tissue samples." (PMID 25946211, 2015). "EGFR mutation, KRAS mutation and ALK expression were investigated in 14 patients whose tumor specimens were available." (PMID 26682906, 2015).
tumor (continued). "Nevertheless, in the settings studied, we propose that redox-dependent reactions with C118 of wild-type KRAS activate the protein to stimulate xenograft tumor growth of oncogenic HRASG12V-driven cell lines." (PMID 25902334, 2015). "Considering that a tumor reaching the size of 1 cm3 is commonly assumed to contain 109 cells or less, this points to the fact that the KRAS-independent phenotype is durable and strong." (PMID 26158412, 2015). "We also give a report on the molecular routes and cellular metabolism, mutation in KRAS and BRAF genes, and other tumor markers in the country." (PMID 25685149, 2015). "This would theoretically lead to increased sensitivity to cetuximab, potentially comparable to tumours with wild-type KRAS." (PMID 26386973, 2015). "Both studies will help to understand the level of acceptance of tumor KRAS/RAS testing by clinicians during their decision processes around treating with panitumumab." (PMID 26491871, 2015). "In KRAS mutated human pancreatic carcinoma cells RALA is found to be necessary for anchorage-independent growth in vitro and for tumor growth in vivo." (PMID 26033452, 2015). "Median progression-free survival was 12.0 months (95% CI: 6.6–17.5 months) in patients with wild-type KRAS tumours and 11.8 months (95% CI: 10.7–13.0 months) in those with mutant KRAS tumours (P= 0.985)." (PMID 25925749, 2015). "The expression level of KRAS in stage III–IVB tumor samples was significantly higher than that in stage I tissue samples (P<0.001)." (PMID 25436011, 2015). "Attenuation of RRM2 expression by let-7b repletion is potentially a promising approach to chemosensitize KRAS mutant tumor cells to gemcitabine." (PMID 25946136, 2015). "To understand the differential effect of let-7b on the wild-type vs. mutant KRAS tumor cells in response to paclitaxel and gemcitabine, we first compared the endogenous levels of let-7b and KRAS in these cell lines." (PMID 25946136, 2015). "Restoration of miRNA-96 in a murine model of human PDAC with subcutaneous implanted MiaPaCa cells reduced tumor growth reducing KRAS pathway activation, suggesting its therapeutic potential in PDAC." (PMID 26259238, 2015). "Today, KRAS and BRAF mutational status is determined in the primary tumor tissues before treatment initiation, however several problems arise." (PMID 25902072, 2015). "Overall, cfDNA analysis showed 89.4% (76/85) concordance for KRAS detection with tumor-tissue analysis (k = 0.753±0.077, p<0.0001)." (PMID 25946211, 2015). "Tumour KRAS status was determined in seventy-one patients (92%); thirty-six patients (51%) had wild-type KRAS tumours and thirty-five (49%) had mutant KRAS tumours." (PMID 25925749, 2015). "Previously-described pathways of CRC development have been suggested to result in tumor subtypes that can be distinguished by specific combinations of MSI, CIMP, BRAF-mutation, and KRAS-mutation status." (PMID 26337942, 2015). "While prior sequencing studies have shown that a small subset of PDA cases harbour wild-type KRAS, the genomic driver(s) of these tumours has remained obscure." (PMID 25855536, 2015). "Among these subgroups, patients with KRAS wild type tumours that are MSI are less likely (p = 0.041) to have disseminated disease." (PMID 25884297, 2015). "The core set of 13 genes common to these three tumor types included key regulators of major oncogenic pathways involved in tumor aggressiveness, including KRAS, EGF3 and PI3K." (PMID 26035357, 2015).
tumor (continued). "In this study, we explore the relative importance of oncogenic KRAS signaling pathways for tumor maintenance and in conferring therapy resistance." (PMID 26158412, 2015). "Medical records review studies carried out in 2010 reported that over 94% of patients were being tested for tumor KRAS status prior to being treated with EGFR-targeted therapies." (PMID 26491871, 2015). "Currently, KRAS and BRAF mutations are routinely tested in tumor tissue by various methods for selection of anti-EGFR therapy in metastatic CRC patients." (PMID 26452027, 2015). "Again, re-expressing the C118S mutant version did not rescue this phenotype, as evidenced by similar tumor growth and tumor size and weight at endpoint in tumors derived from the KRAS-knockdown cells and the KRAS-knockdown cells expressing Flag-KRASC118S." (PMID 25902334, 2015). "As a control, we demonstrate that re-expression of ectopic wild-type KRAS* was more effective than KRAS*C118S at restoring tumor growth of oncogenic HRASG12V-transformed KrasC118S/C118S MEFs." (PMID 25902334, 2015). "In the physician survey, nearly all oncologists (299/301) were aware of the correct panitumumab indication and the need to test patients’ tumor KRAS status before treatment with panitumumab." (PMID 26491871, 2015). "Nearly all patients treated with panitumumab (with or without concurrent oxaliplatin-containing therapy) had wild-type KRAS tumor status confirmed prior to first dose." (PMID 26491871, 2015). "The CN events for this sample are at much higher frequency than 16%, indicating some level of intra tumour heterogeneity where a minor clone has gained a KRAS:p.G12D/V:c.35G > A/T SM." (PMID 25889064, 2015). "As already observed, the reduced tumor growth of the KRAS-knockdown cells was reversed by re-expressing shRNA-resistant wild-type Flag-KRAS, as these cells formed significantly larger (7.3 fold) tumors than the KRAS-knockdown cells." (PMID 25902334, 2015). "Median OS was 14.4 months (95%CI 10.9-19.4) for patients with wild-type KRAS tumor and 10.6 months (95%CI 8.4-12.9) for those with mutant tumor." (PMID 26416458, 2015). "Genome-scale DNA methylation profiling of 125 CRC cases revealed that CIMP-high tumours have high BRAF mutations (61%), whereas CIMP-low tumours rarely have mutant BRAF, but is associated with high KRAS mutations (45%)." (PMID 25622259, 2015). "In the KRAS(G12C) group, all mice had to be sacrificed at day 52 because tumors reached the maximum tumor volume compatible with animal health status (10% of the body weight)." (PMID 26353932, 2015). "In 52 patients, discordance between primary tumor and CTCs was 5.77% for KRAS, 3.85% for BRAF, 11.54% for CD133 rs3130, 7.69% for CD133 rs2286455 and 11.54% for PLS3 rs6643869 mutations." (PMID 25902072, 2015). "To this end, we adjusted clinical variables (tumor location and adjuvant chemotherapy) as well as key molecular variables associated with evolution of CRC (MSI, CIMP, KRAS mutation, and BRAF mutation)." (PMID 25875774, 2015). "This study shows anti-tumor activity with anti-EGFR retreatment in KRAS exon 2-wt CRC patients who had progressed on prior cetuximab- or panitumumab-based treatment." (PMID 26474549, 2015). "We also evaluated the effect of RTA 405-mediated NRF2 activation on KRAS-induced proliferation and the sensitivity of tumor cell lines to other chemotherapeutics." (PMID 26301506, 2015). "We observed a clear decrease in TUBB3 expression at both the transcriptional and translational levels in let-7b-transfected KRAS mutant tumor cells, paralleling with the decline of mutant KRAS in these cells." (PMID 25946136, 2015). "With the exception of the tumor with GNAQ and KRAS co-mutation, all MAPK-activating hotspot mutations appeared to be mutually exclusive of each other and amplifications of MAPK pathway genes." (PMID 26440310, 2015).
tumor (continued). "In agreement with the possibility of differential functional roles of oncogenic KRAS and BRAF mutations during early stages of tumor development, significant correlations with molecular and clinical features have been identified." (PMID 26299805, 2015). "In summary, we have shown that let-7b selectively sensitized KRAS mutant tumor cells to the cytotoxicity of paclitaxel and gemcitabine." (PMID 25946136, 2015). "A total of 157 patients with diverse advanced cancers with known FFPE tumor tissue mutation status for mutations in at least one of the selected cancer genes, which included BRAF, EGFR, KRAS, PIK3CA, were enrolled." (PMID 25980577, 2015). "Another difference observed between KRAS WT and mutant tumor response to PI involved the lipid β-oxidation pathway." (PMID 26709701, 2015). "The ongoing third and final rounds of each study are focusing on tumor RAS (KRAS exons 2/3/4 and NRAS exons 2/3/4) testing, and will be reported separately in a future publication." (PMID 26491871, 2015). "Nonetheless the role of PAK1/PAK2 as potential target for KRAS MT NSCLC, especially for tumor showing dependency from KRAS, merits further evaluation as potential therapeutic target." (PMID 26468985, 2015). "Our choice of inclusion of KRAS as an actionable target relates to the fact that there are early ongoing trials focused on downstream targeting of the MAPK pathway in KRAS mutant patients, making it a potentially actionable target in some tumor types." (PMID 26015395, 2015). "Quantitative DNA methylation analysis demonstrated that approximately 20% of CRCs are CIMP tumours, and there are significant associations with old age, female sex, proximal colon location, poor differentiation, MSI and KRAS and BRAF mutations." (PMID 25622259, 2015). "Overall survival was also similar in patients with wild-type and mutant KRAS tumours: 28.5 months (95% CI: 21.4–35.6 months) versus 27.9 months (95% CI: 21.4–34.3 months), respectively (P= 0.659)." (PMID 25925749, 2015). "We also showed PEAK1 functions downstream of KRas to promote tumor growth, metastasis and therapy resistance using preclinical in vivo models of human tumor progression." (PMID 26267863, 2015). "The present study included patients with KRAS-wt and -mutated tumours that were treated with CTX prior to June 2009, and other patients selected for KRAS-wt tumours that were treated subsequent to June 2009." (PMID 25663927, 2015). "By comparison, Erastin has been reported to exhibit greater lethality in human tumor cells harboring mutations in the oncogenes HRAS, KRAS, or BRAF as well as in an individual genetic context using isogenic cell lines with and without oncogenic RAS genes." (PMID 26157704, 2015). "In 93 sites from France, 94% of 1,044 patients being treated with cetuximab for CRC had been tested for tumor KRAS status, with wild-type KRAS confirmed in 95% of tested patients." (PMID 26491871, 2015). "Combination of let-7b mimic with paclitaxel or gemcitabine diminished MEK/ERK and PI3K/AKT signaling concurrently, triggered the onset of apoptosis, and reverted the epithelial-mesenchymal transition in KRAS mutant tumor cells." (PMID 25946136, 2015). "Ectopic expression of let-7b and let-7g has been shown to repress tumor initiation in KRAS mutant NSCLC in mouse models." (PMID 25946136, 2015).
tumor (continued). "Laboratory use of validated KRAS detection methods: Participating oncologists were asked to name the corresponding laboratories that analyzed the tumor samples." (PMID 26491871, 2015). "The two groups of patients were comparable for age, gender, tumor localization, treatment arm, CT regimen and KRAS status." (PMID 26244985, 2015). "Gene expression profiling reveals that genes involoving epithelial mesenchymal transition and matrix remodeling that can facilitate tumor invasion and metastasis are up-regulated in mutant KRAS-pMMR tumors." (PMID 26042813, 2015). "In mouse models of KRAS mutated prostate cancer, RALB is shown to mediate tumor growth, cell migration and bone metastasis in vivo." (PMID 26033452, 2015). "As an member of KLF family, KLF2 expression is inactivated or lost in several cancers and possesses tumor-suppressor features mediated by KRAS." (PMID 26336870, 2015). "We then predicted that KRAS was a target of miR-200c, which is a member of miR-200 family and usually known to function as tumor suppressors in many cancers." (PMID 26392416, 2015). "PI3K (~40%), KRAS (~20%) and PTEN (~5%) mutations underlie activation in Type I tumours, whereas Type II tumours exhibit frequent copy number changes and over-expression of PI3K/AKT pathway components (~46%)." (PMID 26497682, 2015). "Co-expression of BrafV600E and activated KRAS significantly reduced tumor formation, with this very low tumor burden precluding our ability to observe progression to the adenocarcinoma stage as would be predicted." (PMID 24489653, 2014). "In the Xenopus laevis tadpole model, we used human oncogenes such as mutant KRAS to drive formation of tumor-like structures that exhibited overproliferation, increased nuclear size, hypoxia, acidity, and leukocyte attraction." (PMID 24830454, 2014). "Since the primary tumor of CB42 propagated in both kidney capsule and subcutaneous injections, it suggests that tumor cells containing the KRAS mutation were already present in the primary tumor." (PMID 25162504, 2014). "The mutual exclusive occurrence of KRAS and BRAF mutations suggests they occur in different tumor subtypes." (PMID 25367198, 2014). "Surprisingly there was a significant decrease in tumor number and penetrance with each KRAS effector domain mutant relative to controls, suggesting that KRAS directly activates effectors with tumor suppressive functions." (PMID 24489653, 2014). "MK2206, as well as PI3K inhibitors, have been shown to act synergistically to improve anti-tumor activity in combination with EGFR TKIs in both the KRAS/EGFR WT and EGFR M+ NSCLC setting." (PMID 24946858, 2014). "We next used a pathology tissue ChIP (PAT-ChIP) assay to measure association of ZNF304 with p14ARF, p15INK4B, and p16INK4A promoters in KRAS-positive human CRC tumor samples and, as a control, adjacent matched normal colon." (PMID 24623306, 2014). "This initiative has led to the discovery of some key molecules and pathways including the vascular endothelial growth factor (VEGF) in tumor angiogenesis and the epidermal growth factor receptor (EGFR) with the therapy guiding KRAS/NRAS mutations." (PMID 25261368, 2014). "Their benefit is restricted to patients with a KRAS exon 2 wild type tumor, which recently was further narrowed to RAS wildtype exon 2–4 tumors." (PMID 25375154, 2014). "This tumor was KRAS wild type in the lepidic subtype but KRAS mutant in the minority acinar subtype." (PMID 24742923, 2014).